PPARG (peroxisome proliferator activated receptor gamma)
Diseases named in the same sentence as PPARG in open-access papers (continued):
Sharing a sentence is not in itself a finding about the gene and the disease.
tumor (continued). "The selective inhibition of the noncanonical TGF-β pathway involving MEK-ERK signaling, paralleled by the promotion of adipogenesis and inhibition of tumor-associated inflammation via PPARγ agonists may irreversibly differentiate breast cancer cell into adipocytes." (PMID 35814409, 2022). "Furthermore, PPARγ controls cell proliferation in various other tissues and organs, including colon, breast, prostate, and bladder, and dysregulation of PPARγ signaling is linked to tumor development in these organs." (PMID 33716977, 2021). "Therefore, unravelling novel effectors or modulators of PPARγ could be a promising approach to overcome this obstacle, especially concerning tumours harbouring activating mutations of RAS genes, which are primarily unresponsive to PPARγ activation." (PMID 32522977, 2020). "Collectively, the helix H3 mutations of PPARγ LBD found in various cancers disrupt the sophisticated ligand-binding systems of PPARγ, induce abnormal regulation of PPARγ transactivation and thus may affect tumor development or progression as loss-of-function mutations of PPARγ." (PMID 33266062, 2020). "Similar to smaller studies, just like ours, they investigated whether a number of clinical factors (age, gender, family history, year of diagnosis, tumor stage or grade) were playing a modifying effect on the association between PPARG expression and patient survival." (PMID 32813759, 2020). "The huge difference of PPARγ expression in WD-SCC might be caused by heterogeneity of tumor cells." (PMID 27769068, 2016). "The critical importance of PPARγ in gastric carcinogenesis in vivo has recently been provided: PPARγ heterozygous-deficient mice show an increased susceptibility to carcinogen-induced GC and shorter survival rate than PPARγ wild-type bearing mice, implying a tumor suppressor function." (PMID 22991505, 2012). "In addition, they review that the potential roles of PPARγ and its ligands may play in modulating cancer-associated angiogenesis and tumor-stromal microenvironment crosstalk in the bone marrow." (PMID 20614003, 2010). "However, the role of PPARγ in tumorigenesis have been controversial and the molecular mechanism underlying PPARγ-mediated tumor suppression remains unclear." (PMID 20226009, 2010). "Importantly, lower doses of PPARγ agonists could be used in combination with AB510 to significantly reduce tumor-associated angiogenesis and promote EC apoptosis." (PMID 20204067, 2010). "Althoughthe antiproliferative effects of PPARγ appear to be lost in cells that have eithergerm line or somatic mutations in β-catenin signaling, the data indicate that thisreceptor still retains the ability to inhibit tumor progression, at least inAOM-induced tumors." (PMID 18615192, 2008). "In the TCGA CCA cohort, high expression of IL6, TNF, AKT1, and STAT3 and low expression of PPARG correlated with advanced tumor stage and poorer overall survival (e.g., IL6: ρ = 0.42, p = 0.01)." (PMID 41899527, 2026). "This underscores the importance of cell-type specificity and tumor stage in therapeutic targeting of PPARγ pathways." (PMID 41304753, 2025). "Conversely, PPARD and PPARG showed significantly higher expression in tumor tissue samples, however, only PPARG exceeded the threshold of LogFC>1." (PMID 40860798, 2025). "In cancer, PPARγ has a dual role, sometimes acting as a tumor suppressor, other times as a tumor promoter, depending on the context." (PMID 41476922, 2025). "The addition of the mTOR inhibitor rapamycin reduced IL33-induced LD formation and DGAT1/2 and PPARG expression, as well as the survival ability, proliferation ability, and ability to promote tumor cell proliferation of teHDNs." (PMID 41214328, 2025). "Our results highlight, for the first time, a balanced expression of PPARα and PPARγ along the tumor-derived hepatocyte differentiation/retrodifferentiation process." (PMID 41249163, 2025).
tumor (continued). "Similar results have also been reported for clinically used PPARγ agonists such as pioglitazone, which reduced tumor growth and altered tumor metabolism in xenograft models." (PMID 41403929, 2025). "Through regulation of lipid uptake, fatty acid synthesis, and mitochondrial biogenesis, PPARγ provides metabolic flexibility that supports rapid tumor growth and survival under stress." (PMID 41476922, 2025). "In summary, PPARs, particularly PPARγ, play dual roles in BCa depending on the tumor subtype and microenvironment." (PMID 40806474, 2025). "As a known key mechanism in CC development, OI mediated tumor promoting effects by downregulating PPARG in M0 macrophages and by enhancing the anti-inflammatory profile in M2-like macrophages." (PMID 40552282, 2025). "During tumor-associated macrophage (TAM) polarization toward the M2-like phenotype (protumoral), peroxisome proliferator-activated receptor-γ (PPARγ) and CD36 are upregulated, and FA uptake and oxidation are promoted." (PMID 39402211, 2025). "Treatment with the PPARγ agonist rosiglitazone effectively suppresses tumor growth, and when combined with trametinib (a MEK inhibitor), it induces apoptosis, leading to a significant reduction in tumor size." (PMID 40290121, 2025). "Tumor-derived extracellular vesicles (EVs), enriched with bioactive molecules such as microRNAs, have also been shown to downregulate PPARγ, thereby amplifying adipose tissue catabolism." (PMID 41476922, 2025). "While our study supports its tumor-suppressive function in CRC through PPARγ-mediated inhibition of Wnt/β-catenin signaling and suppression of PKM2-driven glycolysis, contrasting roles have been reported in other cancers." (PMID 40603870, 2025). "Highly expressed in pediatric cancers, PPARγ activation promotes tumor differentiation, inhibits proliferation, and induces apoptosis." (PMID 40370434, 2025). "This shift toward the M2 phenotype, which supports tumor growth and immune suppression, is driven by the upregulation of PPARγ, a nuclear receptor involved in anti-inflammatory responses." (PMID 40330466, 2025). "PPARγ is present in the liver, muscle, and immune cells and possesses the capacity to inhibit inflammation, suppress tumor factors, and regulate immune responses, among other biological functions." (PMID 40298760, 2025). "Agonists of peroxisome proliferator-activated receptor gamma (PPARγ), including pioglitazone and rosiglitazone, have demonstrated significant anti-tumor effects in ACC through multiple mechanisms in preclinical studies." (PMID 40145087, 2025). "In CRC, with tumor progression, increased expression of PPARα and PPARβ/δ or decreased expression of PPARγ." (PMID 39875357, 2025). "Laboratory and animal research, especially in NSCLC models, has consistently demonstrated that pioglitazone, through its activity as a PPARγ agonist, can slow tumor growth, promote cell differentiation, and even prevent progression of early-stage lesions." (PMID 41304753, 2025). "This was consistent with clinical observations, such as higher rates of RAI-resistance in BRAF-positive tumours and follicular architecture in RAS- and PAX8::PPARG-positive tumours." (PMID 40361475, 2025). "PPARγ functions as a tumor suppressor in PCa that induces inhibition of cell growth, decreased tumor invasiveness, and decreased production of proinflammatory cytokines." (PMID 41303378, 2025). "This aligns with accumulating evidence that PPARγ activation can modulate cytoskeletal organization and suppress tumor cell motility." (PMID 41403929, 2025). "Metabolic challenges further compound these issues, as tumor-derived lactic acid suppresses PPARγ expression in iNKT, impairing IFNγ production and anti-tumor function." (PMID 40718496, 2025). "These alterations lead to a dependence on PPARγ for tumor progression, where the formation of the PPARγ/RXRa heterodimer activates pathways that suppress immune cell activity by altering the expression of inflammatory chemokines." (PMID 40806474, 2025).
tumor (continued). "SDA activates peroxisome proliferator-activated receptor gamma (PPAR-γ), acting as a ligand for the nuclear receptor involved in lipid metabolism and tumor suppression." (PMID 40507897, 2025). "Depending on the tumor microenvironment, PPARγ activation can have both tumor-promoting and tumor-suppressive effects." (PMID 40806474, 2025). "Our data indicated that LD synthesis was regulated by PPARγ, as the selective reduction in PPARγ activity directly inhibited LD formation as well as the survival, immune suppression, and tumor-promoting functions of liver-infiltrating M-LDNs." (PMID 41214328, 2025). "This indicates that OCSCs exploit the PPARγ/NF-κB signaling axis to skew macrophages toward a tumor-promoting M2 phenotype." (PMID 40330466, 2025). "PPARG agonists (e.g. rosiglitazone, troglitazone) are substantially involved in cell cycle inhibition, differentiation, proliferation, and migration of tumor cells." (PMID 40500799, 2025). "Tumor‐associated macrophages (TAMs), constituting 30%–50% of the tumor immune microenvironment, drive tumor progression through the STAT6/PPARγ axis‐mediated polarization into the M2 phenotype." (PMID 41360672, 2025). "Clinical data indicate that peroxisome proliferator-activated receptor-gamma (PPARγ) is upregulated in the tumor in 40% of patients resistant to pembrolizumab, and high PPARγ expression is associated with a lower survival rate." (PMID 41514551, 2025). "In Lewis lung carcinoma and C26 tumor models, alpinetin alleviated skeletal muscle wasting through direct activation of PPARγ, as evidenced by reduced MuRF1 and Atrogin-1 expression." (PMID 41476922, 2025). "Previous investigations have indicated that PPARγ is also a potential tumor suppressor in a variety of tissues." (PMID 41019996, 2025). "The contrasting roles of PPARγ in cancer progression reflect its strong context dependency, with outcomes dictated by tumor type, molecular alterations, and microenvironmental cues." (PMID 41476922, 2025). "In fact, PPARγ was identified as a potential therapeutic target for the suppression of tumor growth of OSC by using a murine experimental model with OSC." (PMID 40429934, 2025). "In M0 macrophages, 4OI downregulated the monocyte and T-cell chemoattractant CCL22 and anti-inflammatory marker CD206, and exerted tumor promoting effects by directly downregulating PPARG." (PMID 40552282, 2025). "The in vivo results correlated with in vitro findings, reinforcing that PPARγ activation suppresses both tumor proliferation and angiogenesis by inhibiting chemokine production and NF-κB activity." (PMID 41304753, 2025). "Rosiglitazone administration increased NECTIN4 as well as HPGD (which we used as a surorgate marker of PPARγ activity) in RT112 tumor xenografts." (PMID 40931013, 2025). "In this context, we sought to characterize the metabolic reprogramming that takes place during the differentiation/retrodifferentiation of tumour-derived hepatocytes and specify the role of PPARγ in the metabolic adaptation of hepatic CSCs." (PMID 41249163, 2025). "PPARγ, a nuclear receptor regulating FA metabolism and glucose homeostasis, plays dual roles in lipid metabolism and tumor biology." (PMID 40370434, 2025). "PGC1α inhibited tumor cell glycolysis by downregulating the WNT/β-catenin pathway depending on peroxisome proliferator-activated receptor gamma (PPARγ), thereby suppressing PKM2." (PMID 40603870, 2025). "Furthermore, TFPI2 may promote M2-type tumor-associated macrophages (TAMs) via PPARγ, which support tumor growth through immune evasion, angiogenesis, and ECM remodeling by releasing factors like epidermal growth factor (EGF), hepatocyte growth factor (HGF), VEGF, MMPs, IL-10, and TGF-β." (PMID 40361374, 2025).
tumor (continued). "Among these AR antagonists, PPARγ agonists have demonstrated the potential to inhibit tumor growth by disrupting pathways involved in cellular proliferation, highlighting their therapeutic value in targeting BCa." (PMID 40806474, 2025). "Relevant to all comparisons, when data from larger cohorts are available, interaction modeling to understand the prognostic relevance of PPARγ expression as it relates to tumor subtype and clinical characteristics will be of great interest." (PMID 41236441, 2025). "While classical PPARγ agonists such as TZDs show preclinical promise, their clinical translation is hindered by safety concerns and potential tumor-promoting activity." (PMID 41476922, 2025). "The tumor immune microenvironment was remodeled by PPARG via recruiting and promoting the M2 polarization of macrophages through the CCL2/CCR2 signaling axis." (PMID 40183093, 2025). "Currently, PPARγ agonists were investigated in Phase I/II clinical trials for their anti-tumor effects." (PMID 39834867, 2025). "In tumor-associated macrophages (TAMs), OXPHOS and fatty acid oxidation dominate, mediating H3K4me3 modifications via PPARγ to promote anti-inflammatory genes (e.g., ARG1, MRC1) and drive tumor progression." (PMID 40959285, 2025). "Natural products, as a major source of PPARγ agonists, play an important role in inhibiting tumor cell proliferation and cancer development." (PMID 41019996, 2025). "Highlighting the unique properties of different tumor cells, PPARγ levels were increased after treatments only in cocultures of Hela cells and macrophages, but not in the case of coculture of macrophages with MDA cells." (PMID 41009763, 2025). "miR-130a-3p promotes gemcitabine resistance by targeting peroxisome proliferator-activated receptor gamma (PPARγ), which has tumor-suppressive functions, including cell-cycle arrest and DNA repair." (PMID 41425711, 2025). "PPARγ has emerged as a multifaceted regulator of tumor biology, exhibiting both tumor-suppressive and tumor-promoting activities." (PMID 41476922, 2025). "Decreasing in proliferation, invasion, migration, and EMT of MDA-MB-231 and A375 cancer cells in vitro and BC tumor size in vivo.↓ mRNA stability of PPARG, CEBPA, and CEBPB.↑ mRNA stability of SOCS1.↑ drug sensitivity." (PMID 41157107, 2025). "Fifty-eight HCC tumor tissues were analyzed by immunohistochemistry (IHC), nine of which were positive for PPARγ." (PMID 41249163, 2025). "The observed CRC-specific tumor suppression likely stems from PGC1α’s preferential interaction with PPARγ-a key transcriptional regulator in intestinal homeostasis-rather than alternative partners such as ERRα." (PMID 40603870, 2025). "On the other hand, it has been reported that the PPARγ natural agonist, cladosporols, inhibits adipogenesis in vitro and suppresses tumor proliferation and invasive migration while promoting apoptosis." (PMID 39875357, 2025). "By affecting PPARα, PPARβ, and PPARγ activity, engineered exosomes can reprogram macrophages and impair metabolic support to the tumor, ultimately reducing tumor viability and growth." (PMID 40754671, 2025). "PPARG has been demonstrated to operate as a tumor suppressor by modulating essential biological pathways: metastatic dissemination, suppression of cellular proliferation, and apoptosis across diverse cancer cell lineages." (PMID 40500799, 2025). "Through its regulation of key signaling pathways such as JAK/STAT, mTORC1/HIF-1α, and mTORC2/PPARγ, dioscin effectively inhibits tumor progression while alleviating inflammation and promoting tissue repair." (PMID 40417220, 2025).
tumor (continued). "High FABP5 expression is significantly associated with poor prognosis in pNEN patients, and FABP5 interacts with the PPARγ signaling pathway to enhance tumor cell proliferation and invasion." (PMID 40717587, 2025). "PPARγ is a critical regulator in tumor progression, and its expression is modulated by factors such as miR-27b and TRIM46, which in turn influence its impact on diseases like OS." (PMID 40370434, 2025). "This dualistic nature, protective in peripheral metabolic tissues yet potentially detrimental within the tumor microenvironment, underscores the challenges of therapeutically targeting PPARγ in cancer." (PMID 41476922, 2025). "Across our data, by comparing patients with low tumor PPARγ expression versus high PPARγ expression, we find that typically patients with low expression have worse survival." (PMID 41236441, 2025). "In lipid-rich conditions, NK cells upregulate peroxisome proliferator-activated receptor gamma (PPAR-γ), which partially restores some mitochondrial functions but ultimately leads to decreased anti-tumor activity." (PMID 40806636, 2025). "Research conducted on human tumor tissue has supported that PPARγ expression has a protective effect on CRC, and patients with higher PPARγ expression typically have a better prognosis." (PMID 40603870, 2025). "In mouse models of CRC, deletion of PPARγ in ILC2s led to reduced PD-1 expression, increased anti-tumor immune responses, and better tumor control." (PMID 40963622, 2025). "In the tumor microenvironment, PPARγ fosters immunosuppressive M2 macrophages and increases regulatory T cells, promoting metastasis." (PMID 40361374, 2025). "The biological background to PPARG function in advanced tumour stages, especially metastasis, is still unclear." (PMID 38378472, 2024). "Stimulatory peroxisome proliferator-activated receptor (PPAR)-modulating therapy for TGCT is being investigated with initial positive outcomes, suggesting that PPARγ suppression plays a vital role in the pathogenesis of the tumor." (PMID 38882990, 2024). "PPARG has been shown to play a role in several cancers, and its association with cancer is primarily a result of the recording of PPARG in cancer cells and the tumor cell microenvironmental role." (PMID 39654890, 2024). "This approach impairs tumor growth by modulating redox balance and influencing SIRT1-regulated proteins, such as PGC-1α, PPARγ, and NFκB, altering the tumor microenvironment." (PMID 39796040, 2024). "Studies have shown that PPARG is expressed at low levels in a variety of tumor tissues, and PPARγ can inhibit tumor angiogenesis, inhibit tumor cell proliferation, and promote apoptosis after being activated by ligands." (PMID 38516703, 2024). "PPARG activation terminates tumor growth and metastasis through anti-inflammatory and antiangiogenic cascades." (PMID 38731403, 2024). "We propose that the difference in our results can be attributed to the documented variance in the PPARγ role, which is tumor-, individual-, and concentration-dependent." (PMID 38882990, 2024). "In the present study, the trend toward the upregulation of PPARγ, which was previously reported to act as a tumor suppressor, is related to the clinical features of the analyzed sample." (PMID 39769169, 2024). "Background/Objectives: Peroxisome proliferator–activated receptor γ (PPARγ) plays a key role in mediating anti-inflammatory and anticancer effects in the tumor microenvironment." (PMID 39770941, 2024). "Analysis from the acquired immunofluorescence pictures revealed that PTGS2, MMP9, MMP2, and CXCR 4 were mostly located around the nucleus in tumor tissues, and PPARG was mostly located inside the nucleus in tumor tissues." (PMID 38457601, 2024).